CCND1 (cyclin D1)
Diseases named in the same sentence as CCND1 in open-access papers (continued):
Sharing a sentence is not in itself a finding about the gene and the disease.
breast cancer (continued). "In another study, a TLR3 ligand notably increased breast cancer cell proliferation, as indicated by the upregulation of cyclin D1 expression." (PMID 38347830, 2024). "LINCO1355 interacts with FOXO3a and stabilizes this protein, thereby inhibiting Cyclin D1 expression and inducing cell cycle arrest in the G0/G1 phase of breast cancer cells." (PMID 38505423, 2024). "Overexpression of FOXL1 slows down β‐catenin, c‐Myc, and cyclin D1 expression, inhibiting breast cancer cell invasion and migration." (PMID 38717954, 2024). "Overexpression of CCND1 is often observed in a different spectrum of tumor types, including breast cancer, neck cancer, colorectal cancer, and prostate cancer." (PMID 39273281, 2024). "miR-210 participates in the proliferation of breast cancer cells, particularly triple-negative cells, and is related to lymph node metastases through targets such as CCND1 and RUNX3." (PMID 38813102, 2024). "In breast cancer cells, oleuropein downregulates NFκB and concurrently suppresses cyclin D1, which is one of the most important targets of NFκB." (PMID 39203892, 2024). "Cyclin D1, overexpressed in 50–70% of breast cancers, is an oncogene with pleiotropic effects in the cell." (PMID 38478555, 2024). "Ultimately, our data suggest a strategy to target RRM2, NF-κB protein, and cyclin D1 to supplement traditional therapies while offering improved efficacy for breast cancer treatment." (PMID 38473336, 2024). "Lastly, breast cancer patients with cyclin D1+ and nm23-H1+ reported pCR benefits of 45.8% (n=1) and 29.5% (n=2) than 29.4% (n=1) in cyclin D1− and 5.3% (n=2) in nm23-H1− breast cancer patients." (PMID 38576013, 2024). "Estrogens are believed to stimulate breast cancer cell growth by associating with regulatory elements in the genome, enhancing the transcription of genes such as MYeloCytomatosis (MYC) and CyCliN D1 (CCND1) and promoting tumor cell growth and proliferation." (PMID 38542380, 2024). "Many other oncogenes commonly dysregulated in breast cancer, such as Ras and ErbB2, are upstream of cyclin D1, making cyclin D1 overexpression a good model to probe changes in spindle mechanics after oncogenic transformation." (PMID 38478555, 2024). "MiR-34a inhibited the migration, invasion, and proliferation and modulated drug sensitivity in breast cancer cells by affecting antiapoptotic genes Bcl-2 and CCND1 and the Ras family proteins, NOTCH1 and PRKD1." (PMID 38919953, 2024). "Regions such as 11q13.1 and 17q12.1 in Luminal subtypes are known to harbor oncogenes like CCND1, which drives cell cycle progression and is frequently amplified in breast cancer." (PMID 39596229, 2024). "It has been shown that activated GSK-3β inhibits Cyclin D1 expression in tumor cells, including breast cancer and tongue squamous carcinoma." (PMID 39241034, 2024). "Studies have demonstrated that the expression level of cyclin D1 is elevated in breast cancer stromal cells, prompting fibroblasts to secrete pro-inflammatory factors and osteopontin, facilitating tumorigenesis." (PMID 39544302, 2024). "The CCND1 gene is amplified in approximately 15% of breast cancer cells, and cyclin D1 is overexpressed in up to 67%." (PMID 38256428, 2024). "Our findings advocated the expression of IHC namely, cyclin D1 and claudin-1, in cases of breast cancer." (PMID 40034931, 2024). "Our current study also reports that the CCND1 and RRM2 upregulation associated with palbociclib-resistant breast cancers decreases upon ribonucleotide reductase inhibition." (PMID 38473336, 2024). "It is known that the cell-cycle-regulating protein cyclin D1 is encoded by the CCND1 gene, which influences cell cycle control and accounts for roughly 13% of breast cancers." (PMID 39202273, 2024). "Hereby, our findings advocated the expression of IHC, namely, cyclin D1 and claudin-1, in cases of breast cancer." (PMID 40034931, 2024).
breast cancer (continued). "Quercetin markedly inhibited breast cancer cell proliferation by influencing the G1 phase by downregulating the expression of cyclin D1 and P21." (PMID 38742934, 2024). "The indication of these inhibitors for ER + /HER2- breast cancer can be attributed to the specific dependency of these tumors on cyclin D1 and CDK4/6." (PMID 38831405, 2024). "CCND1 activation of CDK4/6 kinases and its upregulation is associated with ER positivity, poor outcomes, and resistance to endocrine therapy in ER+ breast cancer patients." (PMID 38275906, 2024). "The activated FOXO3a, in a reciprocal manner, elevates the expression of p27Kp1 mRNA and obstructs the expression of Cyclin D1 (also known as CCND1) in breast cancer." (PMID 38505423, 2024). "In a quest for a better, cost-effective approach, researchers proposed the selection of surrogate IHC markers such as cyclin D1 and claudin-1 for the prognosis of breast cancer patients, supplementing the traditional ER, PR, and HER2/neu receptor." (PMID 40034931, 2024). "For example, CCND1, a known oncogene localizes on 11q13, is usually amplified in several types of cancer, such as breast cancer, bladder cancer, and esophageal squamous cell carcinoma." (PMID 38242874, 2024). "The results showed that these NPs significantly downregulated hTERT, Bcl-2, cyclin D1, and survivin, while upregulating caspase-3, caspase-7, and Bax in breast cancer cells, thereby enhancing the antitumor therapeutic effect." (PMID 39555093, 2024). "The expression of CCND1 was found to be more prevalent in breast cancer tumors as compared to normal tissues, as per the differential gene expression seen in clinical patients." (PMID 39202273, 2024). "Acute overexpression of cyclin D1 leads to spindle and karyotypic defects, and long-term overexpression is sufficient to drive breast cancer in mice." (PMID 38478555, 2024). "We also studied the association between cyclin D1 and PIK3CA mutations given the established oncogenic role of cyclin D1 in breast cancer, and its deregulation in our experimental system." (PMID 38273040, 2024). "We also found novel trans-enhancer hijacking events activating known oncogenes including MYC in the small cell lung cancer cell line NCIH146, NOTCH1 in the T-cell lymphoblastic leukemia cell line CUTLL1, and CCND1 in the breast cancer cell line ZR751." (PMID 39033128, 2024). "The lncRNA DILA1, which interacts with Cyclin D1, is found to be upregulated in tamoxifen-resistant breast cancer cells." (PMID 39439957, 2024). "It was reported that it exerted promising effect against breast cancer due to its effect on cyclin D1, D2, D3 and cyclin E leading to controlling the cell cycle progression." (PMID 39478959, 2024). "Although we observed that cyclin D1 overexpression gave rise to higher rates of spindle defects in cultured cells, cyclin D1 is known to be overexpressed in many tumors such as breast cancers." (PMID 38478555, 2024). "It has been seen that cyclin D1 expression acts as a good prognostic and predictive determinant of breast carcinoma." (PMID 40034931, 2024). "Cyclin D1 expression exhibited a statistically significant correlation with nodal status involvement (P=0.011) and with luminal-type breast carcinoma (P=0.023)." (PMID 40034931, 2024). "Another statistically significant correlation was observed between the cyclin D1 expression and luminal-type breast carcinoma (P=0.023), which is in concordance with previous studies." (PMID 40034931, 2024). "This interaction resulted in overexpression of Cyclin D1, leading to lower tamoxifen sensitivity in breast cancer cells." (PMID 37069649, 2023). "miR-107 was shown to negatively regulate NEAT1 expression and regulate breast cancer progression through affecting the tumor development-associated genes, including TIMP-1, PDGF-A, SERPINB2, cyclin D1, CDK4, and CPA1A in breast cancer cells." (PMID 37310654, 2023).
breast cancer (continued). "Previous studies have reported echinacoside to reduce the expression of cyclin D1 in breast cancer cells, but this is the first study to demonstrate its ability to reduce the expression of CDK2." (PMID 37822691, 2023). "A number of epidemiologic studies suggest that cyclin D1 expression is increased in 50% of breast cancers." (PMID 38256865, 2023). "Breast cancer patients usually exhibit a high concentration of thrombin, which promotes the expression of cyclin D1 by activating the mTOR and Wnt/β-catenin signaling pathways." (PMID 36677797, 2023). "Amplification and overexpression of CCND1 preferentially occurred in estrogen receptor (ER)-positive breast cancer." (PMID 37024471, 2023). "It has been reported to arrest cell-cycle progression at the G1/G0 phase in breast cancer cells by up-regulation of p21 and cyclin D1 suppression." (PMID 36674631, 2023). "The cyclin D1 gene (CCND1) is frequently amplified in human breast cancer, and similar to C/EBPβ, has a critical role in the differentiation of mammary epithelial cells during pregnancy." (PMID 36761942, 2023). "This phosphorylation event at ER/S118 enables p38γ to cooperate with c-Jun in binding the cyclin D1 promoter, leading to increased cyclin D1 expression and decreased breast cancer sensitivity to anti-estrogen Tamoxifen (TAM)." (PMID 37443708, 2023). "Atorvastatin decreased breast cancer proliferation via cell cycle regulatory effects through cyclin D1 and p27." (PMID 37760764, 2023). "The QDB method has been used to measure multiple protein biomarkers including ER, PR, Ki67, and cyclin D1 in breast cancer specimens." (PMID 36969021, 2023). "On the other hand, it is known that inhibiting the EAG1 potassium channel suppresses the proliferation of breast cancer cells, arrests cell cycle progression in the G1 phase, and decreases cyclin D1 expression." (PMID 38004441, 2023). "For instance, ID1 promoted lung cancer growth by activating CDK4/cyclin D1 and breast cancer metastasis through S100A9 regulation." (PMID 37759448, 2023). "In contrast, our results show that MC1R activation accelerated S phase entry in breast cancer cells by promoting Cyclin D1 expression." (PMID 37679505, 2023). "For example, miR-93-5p appears to play a role in tumor suppression in ovarian and breast cancers by targeting the PD-L1/CCND1 pathway, which is involved in regulating the cell cycle." (PMID 36982154, 2023). "In breast cancer, CCND1 is frequently overexpressed due to gene amplification or other mechanisms, and its overexpression has been associated with the development and progression of the disease." (PMID 37190123, 2023). "For example, Cyclin D1 is one of the most important oncoproteins that acts an important role in breast cancer cell proliferation and tamoxifen resistance." (PMID 37069649, 2023). "LINC00473 was upregulated in breast cancer in a camp-dependent manner and promoted cell proliferation by regulating CCND1 transcription." (PMID 37901333, 2023). "As a direct downstream target of AKT, GSK3β acts as a tumor suppressor in breast cancer, mediating the expression of cyclin D1 to regulate the cell cycle and increase chemosensitivity." (PMID 36900408, 2023). "C-myc and Cyclin D1 are classical molecular signaling pathways that have been widely studied in malignant tumors such as breast cancer and lung cancer." (PMID 38031136, 2023). "Relative risk of death from breast cancer according to copy numbers of PAK1 and CCND1, and co-amplification of PAK1 and CCND1." (PMID 37368917, 2023).
breast cancer (continued). "As another example, cyclin D1 (CCND1) is an important oncogene that is vital for cell-cycle progression and is thought to have an important role in breast cancer and other tumors." (PMID 37012250, 2023). "For example, translocations between 11q and 17q were observed in 16 out of 25 breast cancers that have co-amplifications of CCND1 and ERBB2, with some cases showing a remarkably similar pattern of copy number and rearrangements." (PMID 37198482, 2023). "It has recently been suggested that CCND1 amplification may be associated with poor response to antiestrogen therapy and that ribociclib and abemaciclib may contribute to increased response rates when combined with endocrine therapy in hormone-responsive advanced breast cancer." (PMID 36675501, 2023). "It has been previously demonstrated that nuclear BAD influences breast cancer cell-cycle progression by preventing cyclin D1 transcription." (PMID 37686282, 2023). "Reducing the expression level of Fascin-1 in breast cancer cells led to a decrease in the expression levels of β-catenin and Cyclin D1, which in turn impacted the growth of tumour cells." (PMID 37015875, 2023). "Other biomolecules exist in breast cancer cells, such as the overexpression of cyclin D1 which phosphorylates LKB1 at Ser325, reversing the autophagy induced by AMPK activation under stress conditions." (PMID 36677797, 2023). "MEK2 controls the activation of the MKK3/MKK6-p38 axis and has an essential impact on the MDA-MB-231 breast cancer cell survival and cyclin D1 expression." (PMID 37445737, 2023). "As ER signaling was potentiated by the BCSC secretome, it was further investigated if the BCSC secretome modulates the expression of CYCLIN D1 as well as the sensitivity to CDK4/6 inhibitor in breast cancer." (PMID 36915147, 2023). "It is important to note that while 4-OH-TMX reduced CCND1 expression in breast cancer cells, it actually increased its expression in endometrial cells." (PMID 38004441, 2023). "CCND1 (cyclin D1) has been solidly established as an oncogene with an important pathogenetic role in breast cancer." (PMID 36927310, 2023). "Cyclin D1 (CCND1) has been found to be overexpressed in breast cancer, and PAK1 is shown to regulate the expression of CCND1 in BC." (PMID 37368917, 2023). "Two of the essential genes in the mitotic cycle are cyclin D1 and cyclin E, over-expressed in 45% and 30% of breast cancers, respectively." (PMID 36072388, 2022). "Compared to raw 2ME, the optimized formula exhibited enhanced anti-proliferative activity in MCF-7 breast cancer cells as evidenced by the down-regulation of cyclin D1 and inhibition of cell cycle progression." (PMID 36143405, 2022). "Cyclin D1 overexpression has been reported in lung cancer, esophageal squamous cell carcinoma, pancreatic cancer, breast cancer, and head and neck tumors." (PMID 35707464, 2022). "Previous studies reported that overexpression of JAK2 in breast cancer promotes cancer cell survival and growth by modulating cell proliferation and apoptosis, partly through the upregulation of cyclin D1 and Bcl-2 family members, such as Bcl-xL and Bcl-2." (PMID 35269680, 2022). "Furthermore, cyclin D1 amplification was significantly associated with clinicopathological variables in breast cancer patients and could be used as an indicator of poor prognosis in breast cancer patients." (PMID 35242498, 2022). "The siRNA against JAG1 reduced cyclin D1 expression and the inhibition of cell cycle progression via cyclin D1-dependent G1/S checkpoint-mediated proliferation in breast cancer cells." (PMID 36012128, 2022). "For the early G1-to-S-phase cell cycle genes, CDK6 and CCNE1 both showed a strong association with TNBC and basal-like breast cancers in all three cohorts, while CDK2, CDK4 and CCND1 expression were high across all patient samples." (PMID 35884422, 2022).
breast cancer (continued). "CCND1 is an influential cell-cycle regulatory protein, and its overexpression is connected with cell proliferation, poor prognosis and recurrence in breast cancer, which has here shown to be downregulated as an effect of the arsenate exposure." (PMID 35563174, 2022). "To further test this, we assessed the effects of Kindlin-2 knockdown on the transcription of cyclin D1, a well-known AR target gene that promotes breast cancer progression and metastasis." (PMID 35595729, 2022). "The knockdown of AATK expression caused a significant increase in CCND1 and WEE1 expression in the breast cancer cell line MCF-7, HEK293T and the melanoma cell line Sk-Mel13." (PMID 35902728, 2022). "CCND1 amplified breast cancer cell lines were more resistant to doxorubicin, and high CCND1 expression levels were associated with non-response in both ER+ and ER− patient samples." (PMID 35523804, 2022). "Luminal B breast cancer is enriched for cyclin D1 overexpression and the chromosomal instability gene signature." (PMID 36358806, 2022). "Stromal cyclin D1 is increased in human breast cancer, correlating with poor outcome, and is known to augment the recruitment of macrophages into the breast cancer tumor microenvironment." (PMID 36358806, 2022). "We selected basally regulated genes (CCND1, PDK4, GREB1) encoding critical regulators of breast cancer progression, and performed RT-qPCRs in unstimulated T47D cells." (PMID 36076907, 2022). "MiR-520e is capable of directly binding to the 3′ untranslated region of Cyclin D1 mRNA to promote the degradation of Cyclin D1 mRNA, leading to the inhibition of cyclin D1 in breast cancer." (PMID 36072972, 2022). "Whereas miR-17-5p is particularly important in breast cancer, the miR-17-5p/miR-20a cluster acts as a tumor suppressor to directly inhibit the expression of amplified in breast cancer 1 and cyclin D1 in human breast cancer." (PMID 35111850, 2022). "In MCF7 human breast cancer cells, GATA3, through its transcription regulation of CCND1 and in association with PARP1 promotes cell proliferation and tumorigenesis by facilitating the G1 to S phase transition in the cell cycle." (PMID 35846378, 2022). "High levels of β-catenin and its target gene, CCND1 were detected in 60% of breast cancers and correlates with poor prognosis." (PMID 35846378, 2022). "Several recent studies addressing cyclin D1 have shown the role of this protein in the development of a substantial proportion of tumors, including breast cancer, as well as the therapeutic management." (PMID 35942997, 2022). "An in silico study has recently suggested that the expression of CCND1 is positively correlated with hormone receptor positivity in most types of breast cancers." (PMID 35622738, 2022). "Conversely, LINC01355 inhibits the growth of breast cancer by inhibiting FOXO3-mediated CCND1 transcription." (PMID 35664432, 2022). "The lncRNA DILA1 functions as a tumor-promoting factor and increases the stability of cyclin D1 to promote breast cancer progression and mediate resistance to tamoxifen." (PMID 35765040, 2022). "Several previous reports have shown that treatment of breast cancer cell lines with FGFR inhibitors downregulates CCND1 and CCND2 expression and inhibits CCND/CDK4 activity, resulting in decreased pRB phosphorylation." (PMID 35884537, 2022).